TLR2 (toll like receptor 2)
Diseases named in the same sentence as TLR2 in open-access papers (continued):
Sharing a sentence is not in itself a finding about the gene and the disease.
infection (continued). "Infection of TLR2 knockout mice with Friend virus (FV), a gammaretrovirus, revealed no impact on viral loads or immunity (E Browne unpublished observation), but genetic evidence from humans has indicated a possible role for TLR2 in HIV infection and disease progression." (PMID 33202596, 2020). "Notably, we have recently determined that E. chaffeensis exploitation of Notch signaling downregulates TLR2/4 expression during infection." (PMID 32353058, 2020). "Surprisingly, dual treatment of MAP-infected macrophages with MyD88 antagonist and nicotine absolutely impaired immune response and decreased MAP viability, which clearly validate the inflammatory role of nicotine in macrophages through TLR2/MyD88 pathway during infection." (PMID 33212859, 2020). "Together, these results indicate that endosomal TLRs were the primary mediators of IL-10 secretion in response to Δhly infection in mice, but that TLR2 may also contribute to induction of IL-10." (PMID 32634175, 2020). "Furthermore, using an in vitro PBMC infection and human vascular endothelium activation models, we investigate the function of TLR2 during DENV infection." (PMID 32576819, 2020). "Moreover; significant association between TLR2 polymorphisms, TLR4 Arg753Gln polymorphisms and risk of infections in AML patients was documented." (PMID 33247673, 2020). "Considering the reduced ability of human primary cell derived DENV2 to engage TLR2 described in our study, it will thus be important to address how both glycosylation and maturation levels of the virions influence TLR2-mediated responses during infection." (PMID 32576819, 2020). "In case of S. aureus parental strain infection in TLR2 deficient mice, there were only ‘bad’ effects – increased metabolic fitness that enhanced the bacterial load but without TLR2-mediated protection, which resulted in the most severe outcome." (PMID 32404866, 2020). "Collectively, these findings suggest that the failure to contain S. aureus burden in the brain and galea during craniotomy infection in TLR2 KO mice may result from the inability to elicit maximal pro-inflammatory mediator production." (PMID 32290861, 2020). "We concluded that MAP relies on TLR2 during infection at least in our macrophage system." (PMID 33212859, 2020). "The participation of TLR2 in the host-cell infection by T. cruzi was then investigated." (PMID 32266161, 2020). "In previous studies we described that infection by the low-virulence isolate Nc-Spain1H induced a higher expression of TLR-2, starting an inflammatory response in bovine trophoblast cells, which may be the cause of the lower proliferation of this isolate." (PMID 31114577, 2019). "Therefore, the large number of unannotated genes of which the expression during infection is dependent on Tlr2 is also worth studying in more detail in future studies." (PMID 31747871, 2019). "Similarly, stable TZMbl-T10 cells transiently over-expressing TLR2 or TLR1 also enhanced proviral pol DNA at 8 h post-infection compared with the empty vector-transient stable cells (P < 0.05)." (PMID 30930906, 2019). "However, in a separate study using a mouse macrophage model, Mtb H37Rv downregulated the TLR2 gene expression after 48 hours of infection." (PMID 31871425, 2019). "Why did we not find the expected differences in susceptibility to infection with B. afzelii between the TLR2 genotypes?" (PMID 31040326, 2019). "In our study, gp43 stimulated PMNs to produce IL-17A only after blocking TLR4, suggesting that gp43 might take advantage of the TLR4/TLR2 interactions during IL-17 production to control inflammatory reactions during an active infection." (PMID 31886295, 2019). "The infection with L.braziliensis increased the expression of TLR2 and TLR4 on monocytes from HS." (PMID 31119102, 2019).
infection (continued). "Additionally, the observation that the presence of Staphylococcus aureus in the lungs of mice prior to Flu infection resulted in reduced mortality was explained by changing TLR2 induced recruitment of inflammatory cells which inhibited the Flu infection." (PMID 31636623, 2019). "At 4 days after Mm infection, the total bacterial burden and the presence of extracellular bacteria were higher in tlr2−/− larvae than in tlr2+/−, or tlr2+/+ larvae, whereas granuloma numbers were reduced, showing a function of Tlr2 in zebrafish host defense." (PMID 31747871, 2019). "We hypothesized that PRV-Becker infection of DRGs that innervate the site of infection, activates the production of G-CSF and IL-6 at very early times post-infection through TLR2 signaling." (PMID 31675371, 2019). "Infection in the murine placenta also increases the expression of TLR2 as a protective mechanism." (PMID 30882005, 2019). "To assess whether infection with T. gondii induced behavioral alternations in the TLR2-/- mice, we conducted the following behavioral experiments: the open-field test, the hole-board test, and the fear conditioning test." (PMID 31404078, 2019). "Inhibition of TLR2 in WT BMDMs only slightly attenuated IL-6 production upon infection with S. pyogenes ATCC12344, whereas cytokine production was completely abolished in Unc93b1 mutant cells and strongly attenuated in Tlr13−/− cells upon additional blocking of TLR2." (PMID 30846984, 2019). "Thus, upregulation of hBD2 induced by TLR2–JNK signaling contributes to protection of the host against infection." (PMID 31681252, 2019). "Of note, enhanced IL-6 secretion in Unc93b1 mutated vs. Tlr13-deficient BMDMs was observed after infection with MOI 50, potentially by compensatory upregulation of TLR2 following its stimulation to counterbalance the loss of all endosomal TLRs under high bacterial load." (PMID 30846984, 2019). "infection, TLR2 mRNA expression decreased compared to 8 dpi (p<0.05)." (PMID 31309100, 2019). "Consequently, knockdown or ectopic expression of FAF1 had a marked effect on production of ROS, proinflammatory cytokines, and antibacterial activity, in macrophages upon stimulation of TLR2 or after infection with L. monocytogenes." (PMID 31412082, 2019). "However, the role played by TLR2 signaling in the chronic stage of infection with T. gondii (more than 6 weeks after the infection) awaits discovery." (PMID 31404078, 2019). "However, we can state that the phenotype of the tlr2 mutant, at the infection level, and the level of transcriptional control such as the mentioned effects on regulation of MafB/c-Maf and chemokines shows a clear connection with macrophage chemotaxis." (PMID 31747871, 2019). "In the later stage of infection, TLR2 contributes to antibacterial defence." (PMID 30452654, 2019). "To verify whether the observed loss in the protein level was dependent on the presence of the surface TLR2 during the phagocytosis process, we used monoclonal anti-TLR2 antibodies prior to the infection to block the TLR2 on the macrophage surface." (PMID 31871425, 2019). "Thus, our aim was to assess the influence of TLR2 and the anaphylatoxin receptors, C3aR1 and C5aR1, during infection with scrapie strain 22L." (PMID 30596651, 2018). "It is likely that the TLR3 induced augmentation of TLR2 activity is absent early times during infection during TLR3 deficiency, and is what contributes to an aberrant immune response to C. muridarum in the TLR3 deficient mice." (PMID 29624589, 2018). "Furthermore, the mRNA levels of RELMa were decreased in liver macrophages from TLR2 KO mice compared with that in WT mice at 4 weeks post-infection, which seemed different from that on stimulation with ES in vitro." (PMID 30589840, 2018). "In addition, TLR2 plays a major role in generating pro-inflammatory responses during infection, mediated by the activation of MAPK and NF-κB signaling." (PMID 29632532, 2018).
infection (continued). "Moreover, a significant decrease in the percentage of infiltrated macrophages and neutrophils (CD11b+Gr-1+ cells) recruitment was observed in infected TLR2-/- mice, compared with that of wild-type mice at 6 weeks post-infection." (PMID 30589840, 2018). "Collectively, our results point to a role of T. cruzi lipids in the induction of a pro-inflammatory response through the TLR2/6 pathway that could contribute to the control of infection and host survival." (PMID 29868507, 2018). "Indeed, in TLR2ko mice infection of the ENS with HSV-1 induced a skewed chemokine response compared with WT mice suggesting that HSV-1 recognition through TLR2 plays a pivotal role in coordinating the initial anti-viral inflammatory response." (PMID 30254622, 2018). "Additionally, the indispensable role ofMyD88 in the generation of protective immunity to L. (V. ) braziliensis-infections in mice should be mentioned here, with TLR2 appearing to have a regulatory role during infection." (PMID 29543867, 2018). "Of note, MYD88, a downstream effector for TLR2 activation of transcription, is also a strong hit in our dependency factor screening suggesting that it is the downstream signaling functions of TLR2 that enhance infection." (PMID 30520725, 2018). "The expression of TLR2 was higher and more lasting in blood after SS2 infection, indicating TLR2 might play a significant role in NETs induction by SS2." (PMID 30581435, 2018). "However, since Tip-DCs were also observed to exhibit T-cell stimulatory capacity in different infection models, the intrinsic ability of Tip-DCs derived from TLR2 and/or TLR9 KO mice to stimulate CD4+ and CD8+ T cells remains to be investigated." (PMID 29760708, 2018). "For example, the protein-free LPS is unable to activate TLR2, whereas the bound LPS on the live bacterium can mediate TLR2 activation via a novel class of lipoprotein lipase-sensitive molecules highlighting the importance of active infection." (PMID 29503705, 2018). "The results indicated that the attenuated virulence of the SCVs in zebrafish could be due, at least in part, to the high levels of cytokines produced in response to infection through TLR2 recognizing up-regulated lipoproteins." (PMID 29594069, 2018). "In particular, it has also been reported that the infection of BCG or Mtb into DCs could lead to enhanced secretion of immune regulatory IL-10 via TLR2-dependent ERK activation, reciprocally suppressing IL-12 secretion." (PMID 29123166, 2017). "Following experimental infection with D. nodosus and vaccination no changes in TLR4 mRNA expression in peripheral blood leukocytes was observed; in contrast, TLR2 mRNA expression levels increased in peripheral blood in leukocytes response to both, infection or vaccination." (PMID 28338081, 2017). "Why could CP-PGN play the role of anti-infection through the TLR2, instead of peptidoglycan of other bacteria?" (PMID 29203871, 2017). "Furthermore, naïve mice challenged with a mouse or a clinical strain of E. gallinarum succumbed to infection through a mechanism involving toll-like receptor-2." (PMID 29375557, 2017). "Free trypomastigotes are equally capable of stimulating IFNs-I released via activation of TLR2 through parasite-derived ligands that may have an impact on the infection outcome by conditioning the host environment and the immune response." (PMID 28824880, 2017). "Macrophages were first pre-treated with blocking anti-TLR2 or anti-CR3 mAbs prior to infection." (PMID 29183333, 2017). "TLR2-deficient mice have reduced Il-1β expression compared to WT at 6 h post-infection with Staphylococcus aureus, but not at 24 h41, suggesting that the role of TLR2 in IL-1β production is most significant in the early stages of infection." (PMID 28824166, 2017). "Moreover, VDR is upregulated during infection in a toll-like receptor 2/1 (TLR2/1)-dependent manner." (PMID 28232830, 2017).
infection (continued). "In gram‐positive pathogens Lpp play a crucial role in infection (Nguyen & Götz, 2016; Takeuchi, Hoshino, & Akira, 2000), sepsis, inflammation, and immune modulation via TLR2‐MyD88 activation." (PMID 28901671, 2017). "Alternatively, MCP-1 down regulation could depend on these receptors, since its mRNA and protein levels are higher in TLR2/9−/− mice than WT mice after infection." (PMID 28222752, 2017). "We observed that the infection induces an ~7.4-fold increase in tlr2 mRNA expression." (PMID 28280488, 2017). "Our study demonstrated that TLR2 could be activated during G. lamblia stimulation in vitro or infection in vivo and it may play an important role on defending G. lamblia infection." (PMID 28979269, 2017). "In addition, a greater percentage of iNOS-producing Mo/Mφ was found in the TG of WT mice during infection compared to TLR2/9−/− infected mice." (PMID 28222752, 2017). "Additionally, these two molecules are TLR2/9 dependent, as TLR2/9−/− mice produce them at low levels, and, in contrast to WT mice, these mice died after infection." (PMID 28222752, 2017). "Infection of the cells for 2 h with either the wild-type or LOS mutant strains was accompanied by a significant increase in TLR2 expression—MFI = 195 ± 28 (wild-type), 178 ± 30 (ΔMMAR_2321), 198 ± 17 (ΔMMAR_2331), 184 ± 9 (∆MMAR_2349), 211 ± 21 (MMAR_2343::Tn)." (PMID 29183333, 2017). "Furthermore, blocking of TLR2-mediated signalling by the use of neutralising antibodies significantly reduced IL-6 expression after infection of A549 cells." (PMID 28195157, 2017). "Likewise, host immune-related genes, such as VCAM1, NFKB1 and TLR2/3, were also elevated at the early stage in the infection group, which were consistent with many previous reports." (PMID 28486945, 2017). "Thus, immune response analyzes in TLR2/9−/− animals were also performed on this day as they beginning to die after the 5th day, which suggests that this day is important for the infection outcome." (PMID 28222752, 2017). "Indeed, in mice deficient for MyD88, the adaptor of almost all TLRs except TLR3, the inflammation upon infection with L. interrogans was equivalent to the inflammation found in double TLR2/TLR4ko mice." (PMID 28270811, 2017). "In contrast, in the infected TLR2/9−/− mice, the high level of granzyme B could be contributing to an exacerbated immune response and the pathogenesis of the infection, contributing to animal death." (PMID 28222752, 2017). "Lactobacilli may contribute in the response against C. albicans colonization and infection by affecting the expression of dectin-1, TLR2, and TLR4 at the transcription level, thus altering the recognition of C. albicans and the cytokine profile of macrophages." (PMID 29238325, 2017). "Indeed, bacterial clearance by TLR2−/− mice was slightly more rapid after intermediate and high‐dose infection than in WT controls." (PMID 29142002, 2017). "In addition, the production of TNF-α, IL-6, and IL-10 was similar between TLR2−/− and WT mice during the early stage of infection (5 dpi)." (PMID 28979269, 2017). "TLR-2 is a pattern recognition receptor whose expression is reported to change during infection." (PMID 27826299, 2016). "It was hypothesized that TLR2−/− mice would display an attenuated disease phenotype upon infection with B. burgdorferi." (PMID 27857714, 2016). "Also, infection with L. braziliensis significantly increased the TLR-2 and TLR4 expression on monocytes in CL patients." (PMID 26840253, 2016). "A time-dependent upregulation of TLR-2 in THP-1 MDM post infection was observed." (PMID 27826299, 2016). "Lungs were isolated from WT and tlr2-null mice after aerosol infection with H37Rv." (PMID 27532872, 2016). "TLR2 is expressed not only in immune cells, but is also present in pulmonary alveoli and airway epithelial cells, suggesting that it plays a role in mucosal innate immunity and infection-induced lung injury." (PMID 27805901, 2016).
infection (continued). "We elicited LCMV primed T cells in congenic wild type mice, purified CD4+ T cells on day 8 post-infection at the peak of T cell expansion, and adoptively transferred the cells into naïve Myd88-/-, IL-1R-/-, TLR2, 3, 4, 7, 9-/-, TLR3, 7, 9-/- and wild type mice." (PMID 27542117, 2016). "Finally, we analyzed if impaired maturation of DC from TLR2, 4 and 9 deficient mice, correlated with a reduced ability to activate B. microti-specific CD8+ Tc cell responses during in vivo infection." (PMID 28119856, 2016). "In contrast, intracellular WCH-SK2SCV infection induced up regulation of only TLR2." (PMID 28083514, 2016). "However, the phenotypes of both amastigote and promastigote infections were strikingly similar, with TLR2−/− mice developing larger lesions in the later stages of infection (promas." (PMID 27716391, 2016). "Our recent studies clearly show the involvement of TLR2–MyD88-dependent pathway, leading to activation of MAPKs, STATs, and NFκB in T. congolense-induced pro-inflammatory cytokine production and resistance to the infection." (PMID 27242788, 2016). "TLR2 initiated the phagocytic process and activated Lyn following infection." (PMID 26735693, 2016). "Activation of B cells via TLR2 in a vaccine strategy may better prepare the immune system to clear an infection." (PMID 30271881, 2016). "Taken together, our study demonstrated that COPD caused the deficiency of AMs function and impaired the activation of TLR2/PI3K/Rac 1 signaling pathway, leading to invasion of Aspergillus infection, which also provides a future basis for the infection control in COPD patients." (PMID 27312383, 2016). "Indeed, infection with the bacteria Klebsiella pneumoniae up-regulates TLR2 and TLR4 on the airway epithelium." (PMID 27309732, 2016). "First, TLR2 was significantly up-regulated within 24–48 hours post-infection (hpi)." (PMID 25955717, 2015). "This has been shown in mice (Myd88-/- and Tlr2-/- mice have significant immune and host defense defects) as well as in humans (TLR2 expression and a Tlr1 polymorphism are associated with altered immune response to B. burgdorferi OspA vaccination and B. burgdorferi RST1 infection, respectively)." (PMID 26252010, 2015). "Considering the highly redundant functions of the TLR2- and Unc93b1-mediated sensing pathways in vitro, we asked whether these pathways were redundant during infection of mice." (PMID 25756897, 2015). "TLR2+CD14+ cell population was up-regulated upon DV infection on day 3 post-infection." (PMID 26226614, 2015). "After treatment, when the infection had been controlled, the expression of TLR2 and TLR4 was still detected, and these TLRs may have been involved in the production of TNF-α, IFN-γ, IL-10 and NO, while TLR4 was involved in the production of IL-17." (PMID 25706930, 2015). "We previously reported that IL-6 was induced via TLR2-dependent pathways in C. muridarum-infected OE cells, and our findings suggest a more critical role for NF-κB in the Chlamydia-induced synthesis of IL-6 throughout the course of infection." (PMID 25798928, 2015). "We observed that infection with both strains led to a higher intensity of HLA-DR and TLR-2 expression by infected monocytes (CD14+CFSE+), as compared to media controls; these increases of intensity did not occur in non-infected monocytes (CD14+CFSE-) from the same cultures." (PMID 26147698, 2015). "If the ELE has insufficient levels of 1,25(OH)2D3, the TLR2/1-mediated immune response could be severely impacted, resulting in decreased infectious agent clearance and increased infection severity." (PMID 27536382, 2015). "In line with our hypothesis that miR-UL112-3p targets TLR2 during infection, the TLR2 decrease correlated temporally with the progressive accumulation of miR-UL112-3p in infected NHDF cells." (PMID 25955717, 2015).